BMP7 (bone morphogenetic protein 7)
Diseases named in the same sentence as BMP7 in open-access papers (continued):
Sharing a sentence is not in itself a finding about the gene and the disease.
breast carcinoma (60 papers, 2007 to 2026). "In CRC, BMP7 variants have been shown to restore chemosensitivity, while in breast cancer, higher BMP7 levels correlated positively with favorable immune profiles and prognosis." (PMID 41395597, 2025). "Alarmo and colleagues reported similar findings of BMP7 mRNA expression in breast cancer tissue as an increase in BMP7 gene copy number was significantly associated with high histological tumour grade and increased proliferation." (PMID 37688374, 2023). "This interpretation is supported by the demonstrated BMP-7 inhibition of estrogen-associated breast cancer cell proliferation via a p38 mitogen activated protein kinase pathway." (PMID 37626268, 2023). "Bone morphogenetic protein 7 (BMP7) is overexpressed in primary breast cancer and has also been identified as being associated with an increased risk of bone metastasis." (PMID 36497209, 2022). "EMT in breast cancer cells is associated with the expression of microRNA-137 which inhibits BMP7 expression resulting in enhanced invasion." (PMID 29799477, 2018). "Β-Gal positivity was observed in the enlarged cells (arrowed) in MCF-7 cell cultures that were treated with BMP7 in 72 h or 96 h, confirming that BMP7 treatment is associated with breast cancer cell senescence." (PMID 27696331, 2017). "Reduced levels of BMP7 in primary breast and lung cancer tissues are significantly associated with the formation of clinically overt bone metastases for breast cancer patients and lymph node metastasis for lung cancer patients." (PMID 26546412, 2015). "Bmp7 has also been implicated in increasing the metastatic potential of 4 T1 mouse mammary tumor cells." (PMID 24156623, 2013). "Previous studies could associate BMP‐7 expression with early bone metastasis development in breast cancer." (PMID 33629769, 2021). "Furthermore, reduced expression of BMP7 in breast cancer has been correlated with increased risk of specifically bone metastases." (PMID 30602372, 2019). "In conclusion, we demonstrate that BMP7 exerts a potent inhibitory effect on telomerase activity and telomere maintenance in human breast cancer cells, causing cancer cell ageing and death, via BMPRII receptor and Smad3 signaling to repression of the hTERT gene." (PMID 27696331, 2017). "Moreover, BMP-7 expression by immunohistochemistry was also significantly associated with lower recurrence-free survival in malignant melanoma and breast cancer." (PMID 21224856, 2011). "Additionally, in vitro studies have implicated BMP4 and BMP7 as important regulators of proliferation and migration of breast cancer cells." (PMID 22118688, 2011). "BMP4 and BMP7, in particular, have been implicated in breast cancer." (PMID 22118688, 2011). "They ultimately demonstrated that BMP7 plays an oncogenic role in tamoxifen-resistant breast cancer cells by modulating MAPK signaling pathways." (PMID 40978031, 2025). "Together, the data show that a modified form of the BMP7‐INHBA feedback loop is present in different subtypes of breast cancer, and that its blockage inhibits the progression of both the triple‐negative and luminal breast cancer subtypes." (PMID 38708713, 2024). "BMP7 has been shown to limit T-cell infiltration and reduce the effectiveness of immune checkpoint inhibitors in breast cancer models." (PMID 38562878, 2024). "For example, BMP2 and BMP6 inhibit cell proliferation whilst BMP7 promotes the proliferation of breast cancer cells." (PMID 37333824, 2023). "BMP7 can inhibit cell proliferation and differentiation of breast cancer cells at primary sites and also in bone." (PMID 37333824, 2023). "Only a small number of studies have investigated the role of BMP7 in human carcinomas, including in prostate cancer, breast cancer, osteosarcomas and malignant melanomas." (PMID 37688374, 2023). "It has been shown that BMP6 and BMP7 can suppress oestrogen-promoted proliferation of the MCF-7 breast cancer cell line." (PMID 37333824, 2023).
breast carcinoma (continued). "Additional evidence for the involvement of BMPs in bone metastasis came from another observation that BMP2/BMP7 heterodimer inhibited colonisation of breast cancer cells in bone." (PMID 37333824, 2023). "From a study by Buijs and colleagues, decreased expression of BMP7 in primary tumours is significantly related to bone metastasis in breast cancer." (PMID 37333824, 2023). "BMP7 is another marker for proliferation, migration, and invasion of breast cancer cells, and BMP7 protein is detected in breast tumors." (PMID 34981672, 2022). "In this article, BMP7 is shown to be able to antagonize the tumorigenic effect of TGFβ1 in breast cancer cells, by reducing the TGFβ1-induced activation of EMT-related genes, cell growth, and metastases." (PMID 33498521, 2021). "By using an in vitro cell system and a mouse model of breast cancer, Balboni and colleagues identified BMP7 as a bona fide ΔNp63 target gene." (PMID 31159154, 2019). "We therefore looked for co-expression of GREM1 and its preferred BMPs, BMP2, BMP4 or BMP7, in human breast cancer cell lines using Expression Atlas." (PMID 31694641, 2019). "Another ΔNp63 transcriptional target involved in breast cancer stemness is BMP7, a member of the bone morphogenetic proteins of the TGFβ superfamily of cytokines." (PMID 31159154, 2019). "Our data support a model in which breast cancer cells that have disseminated to the brain upregulate ID2 expression in response to astrocyte-secreted BMP7 and this serves to support metastatic expansion." (PMID 30642388, 2019). "The BMP7-induced occurrence of breast cancer cell senescence appears several days after treatment, following the inhibition of telomerase activity." (PMID 27696331, 2017). "BMP-7 is able to increase cytokeratin expression, and decrease vimentin in breast cancer cells in vitro and in vivo, leading to an epithelial-like phenotype." (PMID 28733469, 2017). "We recently reported that BMP7 also antagonizes the effects of TGFβ1 in breast cancer (BC) tumorigenesis-related EMT." (PMID 28407692, 2017). "Chonic exposure of human breast cancer cells to BMP7 results in short telomeres, cell senescence and apoptosis." (PMID 27696331, 2017). "Decreased expression of BMP-7 in primary tumours correlates with bone metastases and BMP-7 is able to inhibit the growth of breast cancer tumours in bone in vivo." (PMID 28733469, 2017). "Our finding of BMP7-induced breast cancer cell apoptosis is consistent with previous findings that BMP7 induces the program cell death of myeloma cells and prostate cancer cells." (PMID 27696331, 2017). "To explore BMP7 instigation of breast cancer cell apoptotic cell death, we stained the BMP7 treated cells with annexin V and propidium iodide (PI), and analyzed double positive cells in FACS." (PMID 27696331, 2017). "Pulsatile treatments of breast cancer cells with BMP7 for two weeks are effective to induce a significant shortening of telomeres, marked increase in cell senescence and drastic loss of cultured cells." (PMID 27696331, 2017). "In breast cancer cells, it has been reported that BMP7 inhibits TGFbeta-induced invasion via inhibition of integrin β3, again attesting to the cell-type dependent effect of BMP7 signaling." (PMID 26337467, 2015). "The ability of TOX3 to upregulate a number of genes implicated in breast cancer or mammary gland development, including TBX3, BMP7, and IL17RB, was confirmed by qRT-PCR in transiently transfected cells under estrogen-depleted conditions." (PMID 25632947, 2015). "BMP7 is reported to be upregulated in breast cancer, malignant melanoma, hepatocellular carcinoma, esophageal squamos cell carcinoma and in CRC, where it is associated with poor prognosis and low overall survival." (PMID 25340937, 2014). "BMP7 is also known to display a number of diverse behaviors with regards to cell proliferation, cell migration, invasion and apoptosis in breast cancer cell lines, primary tumors as well as xenografts." (PMID 23721519, 2013).
breast carcinoma (continued). "Functional studies reveal that BMP7 overexpression by breast cancer cells inhibits de novo formation of osteolytic bone metastases and, hence, the metastatic capability of breast cancer cells in in vivo bone metastasis model." (PMID 26237148, 2013). "For instance, BMP7 overexpression has been implicated in EMT in prostate cancer and with increased cell migration and invasion in breast cancer." (PMID 22916288, 2012). "BMP6 has been detected in some breast cancer cells and primary tumors and BMP7 has been reported to be present in different primary breast cancers." (PMID 22729646, 2012). "One of the main goals of this study was to identify new BMP4 and BMP7 target genes relevant in breast cancer." (PMID 22118688, 2011). "The aim of this study was to uncover the transcriptional responses of BMP4 and BMP7 signaling in breast cancer." (PMID 22118688, 2011). "Our experimental approach allowed multiple types of analyses and revealed interesting insights into how the stimulation of BMP4 and BMP7 signaling influences the transcriptome of breast cancer cell lines." (PMID 22118688, 2011). "The present study was designed to gain knowledge in this topic, by exploring the effects of BMP4 and BMP7 signaling on gene transcription in seven breast cancer cell lines and throughout a 6-point time series, using a genome-wide approach." (PMID 22118688, 2011). "We explored the effects of BMP4 and BMP7 treatment on global gene transcription in seven breast cancer cell lines during a 6-point time series, using a whole-genome oligo microarray." (PMID 22118688, 2011). "Their previous studies demonstrated that BMP-7 promoted breast cancer cell migration and invasion, prostate cancer cell mobility and related metastasis in colorectal cancer." (PMID 21224856, 2011). "The expression of BMP4 and BMP7 in breast cancer also has been demonstrated in several other reports." (PMID 22118688, 2011). "All in all, we show that BMP4 and BMP7 have strong effects on gene expression in breast cancer cells, and that this transcriptional response and its functional outcome follow a temporal sequence." (PMID 22118688, 2011). "The functional significance of BMP4 and BMP7 in breast cancer has been studied predominantly through the use of in vitro models." (PMID 22118688, 2011). "The importance of BMP4 and BMP7 in breast cancer was highlighted in a survey of seven BMPs: these two ligands had the highest expression levels and were the most frequently expressed among 22 cell lines and 39 primary tumor samples." (PMID 22118688, 2011). "Our analyses unveiled that treatment of breast cancer cells with either BMP4 or BMP7 resulted in the coordinated expression of a group of genes (clusters A and B, respectively)." (PMID 22118688, 2011). "In order to obtain a general view of the cellular functions regulated as a result of BMP4 and BMP7 signaling in breast cancer cell lines, we performed a GO enrichment analysis on the data sets resulting from general filtering." (PMID 22118688, 2011). "Several studies on the overexpression of BMPs, such as BMP-2, BMP-4, and BMP-7 in mammary tumor cells are suggestive of a role of BMPs in breast cancer development." (PMID 17997862, 2007). "BMP-7 also inhibits tumor growth in an orthotopic xenograft model of breast cancer." (PMID 38892327, 2024). "In addition, there is a positive correlation of BMP-7 with estrogen receptors and progesterone receptors in breast cancer." (PMID 38892327, 2024). "Finally, the BMP7‐INHBA loop also operates in breast cancer, and targeting one or more components of the loop blocks breast cancer progression." (PMID 38708713, 2024). "Especially, BMP4 and BMP7 are two common objects of dormancy study with mouse models, in which it has been discovered that BMP4 could induce dormancy of breast cancer and BMP7 could induce dormancy of prostate cancer." (PMID 34712663, 2021).
breast carcinoma (continued). "Finally, the competition between TGFβ and BMP7 (bone morphogenetic protein-7) for the common signal transducer SMAD4 has pointed out the latter as a promising drug target in breast cancer treatment." (PMID 33498521, 2021). "BMP-7 expression is higher in breast cancer than in prostate cancer." (PMID 34440874, 2021). "Although there is no clear report on whether BMP7 is related to periodontitis and AD in the current study, related studies have proved that BMP7 be related to a variety of tumors, such as colorectal cancer, breast cancer, and prostate cancer." (PMID 34556089, 2021). "BMP7 in breast cancer acts as tumor suppressor and stimulates VEGF expression in prostate cancer." (PMID 32489562, 2020). "Interestingly, BMP7 downregulation in human primary breast cancers is clinically correlated with a tendency to develop bone metastases." (PMID 31547567, 2019). "Systemic administration of BMP7 in breast cancer mouse models has proven to significantly inhibit bone metastases originating from human prostate and breast cancer, by reducing TGFβ-dependent SMAD3/4 activation, activating nuclear signaling of SMAD1/4/5, and restoring E-cadherin levels." (PMID 31547567, 2019). "Notably, activation of BMP7 signaling is a common event observed in human breast cancers, mainly in the basal molecular subtype, where it can regulate EMT, epithelial cell plasticity, and tumorigenicity." (PMID 31159154, 2019). "Downregulation of BMP7 in breast cancer may be attributed to the increased expression of miRNA-137, which is mediated by TGF-β1 signaling." (PMID 29799477, 2018). "Thus, the data together clearly showed that BMP7 induced inhibition of telomerase activity and shortening of telomeres in cultured human breast cancer cells." (PMID 27696331, 2017). "In breast cancer, therapeutic administration of BMP7 could diminish breast cancer metastasis to bone." (PMID 29254283, 2017). "Thus, our data suggest that BMP7 induces breast cancer cell aging by a mechanism involving BMPRII receptor- and Smad3-mediated repression of the hTERT gene." (PMID 27696331, 2017). "Thus, BMP7 employed Smad3 to repress the hTERT gene, inhibit telomerase activity and induce telomere shortening in cultured breast cancer cells." (PMID 27696331, 2017). "Forced gene expression of hTERT inhibits BMP7-induced breast cancer cell senescence and death." (PMID 27696331, 2017). "Expression of hTERT prevents BMP7-induced breast cancer cell senescence and apoptosis." (PMID 27696331, 2017). "With the possible mechanisms of BMP7 action on the cell surface to regulate gene expression programs and cellular phenotypes, we treated cultured breast cancer cells with BMP7 overnight with repeats in every two-day for two weeks and examined cell senescence and death." (PMID 27696331, 2017). "To investigate a potential involvement of the BMP family in telomerase activity, we examined the effects of BMP2, BMP4, BMP5, BMP6 and BMP7 on telomerase activity by spiking the medium of cultured human breast cancer MCF-7 cells with purified recombinant human cytokines." (PMID 27696331, 2017). "In addition to stimulating Smad1, Smad5 and Smad8 phosphorylation and nuclear translocation, BMP7 also induces Smad3 phosphorylation and nuclear accumulation in breast cancer cells and silencing Smad3 abrogates BMP7-induced telomerase inhibition." (PMID 27696331, 2017). "Thus, similar to what has been reported for lung cancer, melanoma and, albeit controversial, for breast cancer, BMP7 exerts a tumor-promoting action in PCC." (PMID 26337467, 2015). "Decreased BMP7 expression during breast cancer progression may, therefore, contribute to the acquisition of a bone metastatic phenotype." (PMID 26237148, 2013). "These clinical findings suggest that decreased BMP7 expression may confer a bone metastatic potential to human breast cancer cells." (PMID 26237148, 2013). "Furthermore, exogenous BMP7 can still inhibit breast cancer growth at the primary site and in bone marrow." (PMID 26237148, 2013).
breast carcinoma (continued). "An additional finding that could be inferred from our data is that induction of gene transcription, compared with inhibition, was the common response among those genes most frequently regulated by BMP4 and BMP7 in breast cancer cells." (PMID 22118688, 2011). "MiR-137 also was demonstrated that could inhibit BMP7 to enhance the EMT of breast cancer cells." (PMID 33718112, 2020). "Thus, over and above hTERT repression, other mechanism(s) may exist to participate in mediating BMP7-induced breast cancer cell senescence as well as apoptosis." (PMID 27696331, 2017). "Interestingly, this may possibly be extended beyond lung cancer and involve also metastatic breast cancer growth into the lungs of experimental animals driven by BMP7 signaling, as previously demonstrated." (PMID 26701726, 2016). "Therefore, BMP7 may represent a novel therapeutic molecule for repression of local and bone metastatic growth of human breast cancer." (PMID 26237148, 2013). "Elevated BMP7 levels are reported to be correlated with the depth of colorectal tumor invasion, liver metastasis and cancer-related death, as well as the levels of estrogen and progesterone receptor, both of which are important markers for breast cancer prognosis and therapy." (PMID 24161199, 2013). "In the bone marrow niche, mesenchymal stem cells (MSCs) induce breast cancer cell dormancy by secreting transforming growth factor-β2 (TGF-β2) and bone morphogenetic protein 7 (BMP7), which activate the TGFBRIII/BMPRII-p38-p27 pathway." (PMID 41484089, 2026). "Nature Cancer.The paper identified that perivascular MSCs promote dormancy of disseminated breast cancer cells via TGF-β2 and BMP7." (PMID 41091336, 2025). "BMP2, BMP4, GDF11 and TGFBR2 had relatively higher levels in bone metastases of breast cancer while BMP5, BMP7, BMPR2, BMPR1A and ACVR2A presented lower expression in the bone metastases, in the E-MTAB-4003 dataset." (PMID 37333824, 2023). "In summary, a shift in the expression pattern of BMPs in breast cancer, including increased BMP8A, BMPR1B and decreased BMP6, BMP7, ACVR1C, TGFBR2, TGFBR3 and BMPR2 presented a subtype specific role." (PMID 37333824, 2023). "BMP7, GDF15, BMP5, SMAD6 and FSTL5 were highly expressed in the ER positive breast cancer cells (MCF-7 cells), while the expressions of TGFBR2, FSTL1 and NOG were reduced in this cohort." (PMID 37333824, 2023). "Bone morphogenetic protein 7 (BMP7) is reported to trigger MET in renal fibroblasts during kidney development, and also in breast cancer cells, reducing their capability to form bone metastases." (PMID 32391381, 2020). "We found that BMP7 knockdown in anti-PD1-resistant 344SQR model and in 4T1 mouse mammary carcinoma model sensitized tumors to anti-PD1 and extended survival relative to the control." (PMID 32973129, 2020). "Some BMPs, such as BMP7 and BMP4, can induce dormancy in prostate and mammary carcinoma cells, respectively." (PMID 31547567, 2019). "Further, our findings that BMPRII receptor mutant blocks BMP7-induced repression of the hTERT gene promoter in both MCF-7 and PMC42 breast cancer cells demonstrate a BMP7- BMPRII receptor pathway in a negative regulation of the hTERT gene." (PMID 27696331, 2017). "SOSTDC1, a secreted regulator of both BMP and Wnt signalling pathways, is under expressed in breast cancer and can differentially affect signalling induced by Wnt3a, BMP-2 and BMP-7." (PMID 28733469, 2017). "Here we report that the cytokine bone morphogenetic protein-7 (BMP7) induces the hTERT gene repression in a BMPRII receptor- and Smad3-dependent manner in human breast cancer cells." (PMID 27696331, 2017). "In breast cancer cells, SOSTDC1 modestly increases Wnt3a signalling, decreases BMP-7 signalling, whilst eliciting little effect on BMP-2-induced signalling." (PMID 28733469, 2017). "By forming a heterodimer with BMP7, BMP2 acts as a TGF β antagonist and prevents bone metastases in a mouse model of breast cancer." (PMID 24944582, 2014).